GIP (gastric inhibitory polypeptide)
Diseases named in the same sentence as GIP in open-access papers (continued):
Sharing a sentence is not in itself a finding about the gene and the disease.
Obesity (continued). "With the advent of more effective pharmacotherapy for obesity, particularly glucagon-like peptide (GLP-1) agonists and dual GLP-1/GIP (glucose-dependent insulinotropic polypeptide) agonists, questions have been raised about the role of surgery in the future treatment of obesity." (PMID 40381136, 2025). "Although not fully understood, both GIP agonism and antagonism surprisingly benefit obesity-diabetes but neither approach is superior to the substantial benefits of recently introduced unimolecular peptides targeting both GIP and GLP-1 receptors." (PMID 40024571, 2025). "This study aimed to assess the effectiveness of combining glucagon-like peptide-1 (GLP-1) and dual gastric inhibitory polypeptide (GIP)/GLP-1 agonists with a continuous, digitally delivered behavioral change model by an integrated care team, in treating MetS among individuals with obesity." (PMID 40146920, 2025). "Whilst GIP's eponymous role in regulating insulin release is clear, the effect on energy balance of GIP remains unclear: both GIPR knockout and GIP-overexpressing mouse models are protected from high-fat diet induced obesity." (PMID 39788289, 2025). "Obesity remained slightly more common among non-GLP/GIP users (69.2% vs. 67.7%; p = 0.004; SMD = 0.032), though still within acceptable matching thresholds." (PMID 41464784, 2025). "Taking into account the fact that there is a close relationship between obesity, PPAT, and prostate cancer, a new field is opened for research aimed at explaining GIP as well as GLP-1 agonist and what effect the novel agents used in the treatment of obesity have on the biology of prostate cancer." (PMID 39941741, 2025). "To date, no reports on the use of the novel dual GIP/GLP1 agonist tirzepatide on individuals with this rare obesity syndrome have been published." (PMID 40302276, 2025). "It has been found that retatrutide, a 39 amino acid peptide, can resist cleavage by dipeptidyl peptidase IV, which is responsible for breaking down GLP-1 and GIP,271 and it also stimulates GLP-1, GIP and glucagon receptors, which is potentially useful for treating obesity and T2DM." (PMID 40038239, 2025). "Tirzepatide is a once weekly, single molecule dual glucose‐dependent insulinotropic polypeptide (GIP) and glucagon‐like peptide‐1 (GLP‐1) receptor agonist approved in adults for the treatment of T2D, obesity, and (in the US) moderate to severe obstructive sleep apnea in patients with obesity." (PMID 40916045, 2025). "Recently, chronic administration of the dual GIP and GLP-1 receptor agonist in mice with diet-induced obesity potently decreased body weight and appetite, and these effects were significantly greater compared to that with GLP-1 receptor agonist treatment alone." (PMID 39940910, 2025). "Glucagon-like peptide-1 (GLP-1) and, more recently, glucose-dependent insulinotropic polypeptide (GIP) and glucagon (Gcg) receptor (R) agonists have revolutionized T2DM and obesity treatment, restoring insulin sensitivity and often facilitating weight loss in patients." (PMID 39062586, 2024). "The second dual GIP/GLP-1 receptor agonist, tirzepatide (previously known as LY3298176; marketed as Mounjaro® for T2DM and Zepbound® for obesity), is a 39-amino acid peptide acylated with a C20:0 fatty diacid moiety to lysine residue at position 20 with a molecular weight of 4.8 kDa." (PMID 39114288, 2024). "The potential mechanisms through which GLP-1 and GIP/GLP-1 receptor agonists recalibrate and normalize the fat mass and body weight setpoint in patients with obesity may stem from their primary effects on incretin homeostasis." (PMID 39114288, 2024). "The development of obesity in mice fed WD was also reflected by the significantly increased plasma levels of the hormones leptin, peptide YY (PYY), resistin, and glucose-dependent insulinotropic polypeptide (GIP)." (PMID 38469142, 2024).
Obesity (continued). "In the SURMOUNT-OSA phase 3 trials, tirzepatide, a new GIP/GLP-1 receptor co-agonist, reduced the apnea–hypopnea index, hypoxic burden, and body weight in adults with moderate-to-severe obstructive sleep apnea and obesity." (PMID 39378016, 2024). "There are multifaceted effects of GIP on ATBF and vascular function; however, further investigation on rodents with obesity and T2DM will help understand whether the effects of GIP are consistent across different pathological conditions." (PMID 38579777, 2024). "Subsequently, we assessed whether the infection status had an impact on the metabolic efficacy of best-in-class drugs to treat obesity and diabetes, namely the GLP-1 receptor agonist liraglutide and the GLP-1/GIP co-agonist MAR709." (PMID 39019114, 2024). "Tirzepatide, a glucose-dependent insulinotropic polypeptide (GIP) receptor and glucagon-like peptide-1 (GLP-1) receptor agonist, is indicated for chronic weight management in adults with obesity or overweight as an adjunct to a reduced-calorie diet and increased physical activity." (PMID 38910884, 2024). "Furthermore, tirzepatide, characterized as a dual agonist targeting GIP and GLP-1, has exhibited efficacy in weight reduction and recently secured approval from the Food and Drug Administration for managing both T2D and obesity." (PMID 39318607, 2024). "The authors observed that individuals with obesity exhibit reduced GIP activity in SAT, but not in VAT." (PMID 39408213, 2024). "GIP was higher in leaner individuals and was upregulated after a MMT, while C-peptide and its overall AUC after a MMT was markedly elevated in people with obesity compared with lean subjects." (PMID 38762719, 2024). "The approval of incretin-based therapies, including the glucagon-like peptide-1 (GLP1) receptor agonists Liraglutide and Semaglutide, and the glucose-dependent insulinotropic polypeptide (GIP) and GLP1 dual agonist Tirzepatide, has brought new hope for the medical management of obesity." (PMID 38202263, 2024). "Taken together, drugs engineered to promote GIP, GLP-1 and GLP-2 receptor signalling may have potential to offer therapeutic promise for improving bone health in obesity and diabetes." (PMID 38486712, 2024). "For the treatment of obesity and diabetes, unimolecular peptides that target the glucagon-like peptide-1 (GLP-1) and glucose-dependent insulinotropic polypeptide (GIP) receptors (GLP-1/GIP co-agonist) are now being tested in clinical settings." (PMID 37375734, 2023). "Neither of the metabolic effects induced by GLP-1 or GIP was observed in the VAT of subjects with obesity with or without concomitant dysglycemia." (PMID 37233628, 2023). "GLP-1 (Glucagon-like peptide-1) and GLP-1/GIP (Glucose-dependent Insulinotropic Polypeptide) agonists, FDA-approved for managing type 2 diabetes and obesity, where the former has shown to effectively reduce the consumption of alcohol in animal models but no reports exist on the latter." (PMID 38017205, 2023). "Interestingly, the dual‐based GIP/GLP‐1 agonists are under further study for joint treatment of T2DM and obesity." (PMID 37522521, 2023). "Moreover, a rationally constructed tri-agonist that mimics the activity of GLP-1, GIP and GCG in one single poly-receptor agonist is able to dramatically improve the outcome of both obesity and diabetes." (PMID 36552107, 2022). "Treatments that regulate metabolism, particularly gastrointestinal hormones, are becoming increasingly common; for example, GIP plus glucagon or a triagonist comprising GIP, GLP-1 and glucagon is also being developed for patients with obesity, diabetes or dyslipidaemia." (PMID 35949358, 2022). "Recently, 15 mg tirzepatide, a novel dual glucose-dependent insulinotropic polypeptide (GIP) and glucagon-like peptide-1 (GLP-1) receptor agonist, reduced the body weight of patients with obesity by 20.9% from baseline compared with placebo in the SURMOUNT-1 trial." (PMID 36068534, 2022).
Obesity (continued). "Altered production or action of gut hormones, including glucagon-like peptide-1 (GLP-1), glucose-dependent insulinotropic polypeptide (GIP) and peptide YY (PYY), may contribute to the biological basis of obesity and altered glucose homeostasis." (PMID 33175577, 2021). "Notably, the co-administration of the GLP-1 receptor agonist and GIP in mice with T2DM and obesity showed a greater improvement in glycemic and body weight than with selective GLP-1 receptor agonists." (PMID 34681215, 2021). "GIP secretion in response to oral fat is greater in patients with obesity and glucose intolerance, and does not change with the addition of glucose to the meal." (PMID 34660576, 2021). "Indeed, our study provides the novel finding that density of GLP-1-positive cells is reduced in jejunum in T2D individuals with severe obesity whereas CCK-, GIP- and PYY- producing cell densities remained unaffected." (PMID 33037328, 2021). "The combination of GLP-1 and GIP agonists for improved treatment of obesity has also been studied; however, the results are not consistent." (PMID 33503878, 2021). "Because improving glucose control with antidiabetic therapies appears to restore the insulinotropic effect of GIP in patients with T2D, growing evidence suggests that GLP-1R/GIP-R co-agonists could represent a promising strategy for treating T2D and obesity." (PMID 33671882, 2021). "Finally, GIP, K cell, and GIPR knockout mice are resistant to high-fat diet (HFD)-induced obesity and insulin resistance." (PMID 33788878, 2021). "Studies employing intraduodenal infusion of nutrients at different rates that mimic the physiological range of gastric emptying have shown that the secretion of GIP and CCK increases in an approximately linear pattern with increasing rates of infusion in health, obesity and T2DM." (PMID 32825608, 2020). "In human plasma, GIP levels are increased with obesity and correlate with body mass index, but the exact role of GIP in the development of obesity and diabetes is not fully understood and various concepts are suggested." (PMID 32069846, 2020). "Indeed, any blockade of the GIP signal and/or hyperinsulinemia is a protection from high-fat diet (HFD)-induced obesity in mice." (PMID 31083314, 2019). "As glucose-dependent insulinotropic polypeptide (GIP) possesses pro-adipogenic action, the suppression of the GIP hypersecretion seen in obesity might represent a novel therapeutic approach to the treatment of obesity." (PMID 31509948, 2019). "GLP-1 and GIP are responsible for a large proportion of GSIS, and both are reduced in obesity." (PMID 29865281, 2018). "In our previous study, we found that the dietary components that control GIP secretion, such as diacylglycerol, 1-monoolein, and RS4-type-resistant starch, increase postprandial fat utilization and prevent high-fat diet-induced obesity in mice." (PMID 28970776, 2017). "The results of our current study also suggest that the postprandial GIP and active ghrelin responses are reliable predictors of postprandial REE and might be used as markers for designing obesity-preventive meals." (PMID 27112963, 2017). "Unlike its incretin counterpart GLP-1, GIP alleviated obesity through increased energy expenditure but did not affect food intake." (PMID 28223965, 2017). "Such an effect would be consistent with the lipogenic actions of GIP and with studies demonstrating that mice lacking functional GIP responses show resistance to the development of obesity." (PMID 20231880, 2010). "Dual glucagon-like peptide-1 (GLP-1) and glucose-dependent insulinotropic polypeptide (GIP) receptor agonists have emerged as a novel therapeutic class with potential relevance for cardiovascular prevention, particularly in the context of obesity and type 2 diabetes mellitus." (PMID 41930072, 2026).
Obesity (continued). "However, the potential benefits of GLP-1RAs and dual GIP/GLP-1 RAs in patients with HFrEF or ASCVD without excess weight/obesity remain unexplored, and further studies are needed to assess their effectiveness." (PMID 40283662, 2025). "In individuals who were metabolically healthy and with obesity (gastric banding = 8 or RYGB = 10), the MMT responses of plasma glucose, insulin, and c-peptide (to estimate hepatic insulin extraction; %HIE), incretins (GIP, aGLP-1), and PP were assessed 4–8 weeks prior to and following surgery." (PMID 41155711, 2025). "However, our data suggest that in AS when GLP1 mono agonists do not lead to sustained weight loss, a switch to the dual GIP/GLP1 agonist tirzepatide should be considered, especially when obesity-related comorbidities are present." (PMID 40302276, 2025). "Likewise, the administration of GIP does not induce obesity although GIP is considered an obesity hormone." (PMID 39940910, 2025). "The study of GIP may be of particular interest going forward since this product of K cells may be affected by the use of GLP1-agonists in the treatment of diabetes and obesity." (PMID 40553402, 2025). "Incretin-based therapies represent a novel treatment for both T2DM and obesity, relying on the insulinotropic actions of the gut hormone glucagon-like peptide-1 (GLP-1) and, most recently, on the combined action of GLP-1 and the gastric inhibitory polypeptide (GIP) hormones." (PMID 40566497, 2025). "Furthermore, native GIP infusion alone fails to reduce food intake in patients with obesity nor does it drive additional reduction in energy intake when paired with the GLP-1R agonist liraglutide." (PMID 40507574, 2025). "However, there has been a rekindling of interest in GIP biology in recent years, in great part due to pharmacology demonstrating that both GIPR agonism and antagonism may be beneficial in treating obesity and diabetes." (PMID 40024571, 2025). "Patients with obesity and T2DM undergoing Roux-en-y Gastric Bypass (RYGB) had an early improvement in glucose levels and insulin resistance, together with an increase in Glucagon-Like Peptide-1 (GLP-1) and Glucose-dependent Insulinotropic Polypeptide (GIP) a few days after surgery." (PMID 40902424, 2025). "Discrepancies in the literature—ranging from reports of exaggerated GIP responses in individuals with obesity to findings of no significant variation—may stem from differences in study design, insulin sensitivity, and participant characteristics." (PMID 40806130, 2025). "Additionally, the potential benefits of GLP-1RAs and dual GIP/GLP-1RAs in patients with HF or ASCVD but without overweight/obesity remain unexplored and represent an important avenue for future research." (PMID 39857719, 2025). "Furthermore, tirzepatide, a novel dual GIP/GLP-1 RA, has shown remarkable efficacy in the management of obesity, in delaying the onset of T2DM among individuals with prediabetes, in reducing HbA1c levels, and improving obesity-related obstructive sleep apnea (OSA)." (PMID 41303740, 2025). "Interestingly, in chronic hyperglycemia, IR, T2D, and obesity, the GIP signaling is impaired and not able to inhibit appetite and metabolic derangements." (PMID 40498212, 2025). "Preferred options for the treatment of comorbidities are GLP-1 RAs, tirzepatide (dual GIP/GLP-1 RA), SGLT2is, metformin or insulin (in case of decompensated cirrhosis) for T2D; statins for dyslipidemia; and GLP-1 RAs, tirzepatide (dual GIP/GLP-1 RA) for obesity." (PMID 40316962, 2025). "Recently, tirzepatide, a novel dual glucose-dependent insulinotropic polypeptide (GIP) and glucagon-like peptide-1 (GLP-1) receptor agonist, has demonstrated considerable efficacy in improving glycemic control and promoting weight reduction in patients with obesity." (PMID 41334076, 2025).
Obesity (continued). "Lastly, the lack of data on lifestyle and socioeconomic variables, including diet, exercise, and financial constraints, may confound outcome interpretation.In mild obesity post-MS, liraglutide 3.0 mg/day or GLP-1/GIP dual agonists may be required for optimal results." (PMID 40475994, 2025). "In addition, normal chow‐fed DIO mice were also investigated and it was found that after 14 days, the mice SC injected with GIP/ICG@P/R8 NPs and followed by the NIR‐I laser irradiation also inhibited obesity development with a 23.48% weight reduction, in line with the previous examination." (PMID 41256211, 2025). "Tirzepatide, characterized by its ability to selectively bind and activate receptors for the intestinal hormones GIP and GLP-1, has been tested in numerous clinical studies and is already currently authorized in several countries for the treatment of type 2 diabetes and obesity." (PMID 38831203, 2024). "The incretin hormones glucose-dependent insulinotropic polypeptide (GIP) and glucagon-like peptide-1 (GLP-1) play a particularly important role in glucose metabolism and regulation of food intake and body weight, as evident from their development as therapies for type 2 diabetes and obesity." (PMID 38240302, 2024). "Furthermore, this study does not compare the efficacy and safety of elocalcitol with newer anti-obesity agents, such as GLP-1 receptor agonists (e.g., semaglutide) or dual GLP-1/GIP agonists (e.g., tirzepatide), which are widely used and administered weekly via parenteral routes." (PMID 39898321, 2024). "Participants with healthy BMI (n=15), overweight BMI (n=29) and obesity (n=161) had samples taken fasting and 30 min post mixed liquid meal for analysis of glucagon-like peptide-1 (GLP-1), PYY, glucose-dependent insulinotropic polypeptide (GIP), insulin and glucagon." (PMID 38490484, 2024). "While early studies demonstrated the clinical potential of GIPRA in rodent models of type 2 diabetes/obesity, development of GIP agonists for human use was largely curtailed by GIPR downregulation, the lack of glycemic benefit of GIPRA, as well as the concept that GIPR agonism drives obesity." (PMID 38360354, 2024). "Additionally, tirzepatide, a glucose-dependent insulinotropic polypeptide (GIP)/GLP-1 dual agonist, has proven efficacy in weight reduction and was recently approved by the Food and Drug Administration (FDA) for treating type 2 diabetes (T2D) and obesity." (PMID 39420937, 2024). "Through its unique mechanism of action as a glucose-dependent insulinotropic polypeptide (GIP) and glucagon-like peptide-1 (GLP-1) receptor agonist, as well as its impressive results in clinical trials, tirzepatide has the potential to completely transform the current approach to treating obesity." (PMID 38887332, 2024). "The primary aim of this study was to evaluate whether plasma concentrations of glucagon, total GLP-1, and total GIP during an OGTT differ between children and adolescents with obesity and insulin resistance (OIR), obesity and normal insulin sensitivity (OIS), and controls with NW." (PMID 38087928, 2024). "Compared to controls, bipolar disorders showed lower serum glucagon and glucagon-like peptide (GLP-1) levels and higher gastric inhibitory polypeptide (GIP) levels, suggesting alterations in glucose metabolism, which may contribute to the elevated obesity rates in bipolar disorders." (PMID 40226675, 2024). "However, unlike GLP-1, GIP is less studied and has not yet become a pharmacological therapy for the treatment of obesity or NAFLD." (PMID 36732495, 2023). "In the VAT of individuals with obesity and prediabetes, GLP-1 shifted its metabolic profile by increasing alanine and lactate production while also decreasing isoleucine consumption, whereas GIP and glucagon decreased lactate and alanine production and increased pyruvate consumption." (PMID 37233628, 2023).